PAPPA (pappalysin 1)
Description:
Metalloproteinase which specifically cleaves IGFBP-4 and IGFBP-5, resulting in release of bound IGF. Cleavage of IGFBP-4 is dramatically enhanced by the presence of IGF, whereas cleavage of IGFBP-5 is slightly inhibited by the presence of IGF.
Synonyms: IGFBP-4ase; PAPP-A; PAPPA1; PAPA; ASBABP2; DIPLA1
Tractability: Antibody: UniProt places it where antibodies can reach, with high confidence; its Gene Ontology location is reachable by antibodies, with high confidence; UniProt predicts a signal peptide or a membrane-spanning region. PROTAC: ubiquitination databases record sites on it.
Gene: Protein-coding gene on chromosome 9 (116,153,791 to 116,402,321, forward strand). Ensembl gene ENSG00000182752.
Subcellular location: Secreted
Pathways (Reactome):
Metabolism of proteins: Regulation of Insulin-like Growth Factor (IGF) transport and uptake by Insulin-like Growth Factor Binding Proteins (IGFBPs)
Gene Ontology:
Molecular function: metalloendopeptidase activity; metallopeptidase activity; protein binding; zinc ion binding; endopeptidase activity
Biological process: cell surface receptor signaling pathway; female pregnancy; proteolysis
Cellular component: extracellular region
Genetic constraint (gnomAD): Loss-of-function variants: 48 observed, 130.82 expected, observed/expected ratio (o/e) 0.37, 90% interval 0.29 to 0.47. The upper end of that interval is the gene's LOEUF score, 0.47, which puts it in group 2 of 6, group 1 being the genes least tolerant of losing a copy. Missense variants: 1,478 observed, 1,805.8 expected, observed/expected ratio (o/e) 0.82, 90% interval 0.78 to 0.85. Synonymous variants: 734 observed, 708.38 expected, observed/expected ratio (o/e) 1.04, 90% interval 0.97 to 1.1.
Homologues: Orthologues: chimpanzee PAPPA (98% identical), macaque PAPPA (97% identical), pig PAPPA (93% identical), dog PAPPA (93% identical), rat Pappa (92% identical), mouse Pappa (91% identical), guinea pig PAPPA (87% identical), rabbit PAPPA (84% identical), tropical clawed frog pappa (68% identical), zebrafish pappab (60% identical), zebrafish pappaa (59% identical). Paralogues in human: PAPPA2 (44% identical), CSMD2 (11% identical), CFH (11% identical), CSMD3 (11% identical), CSMD1 (11% identical), SVEP1 (10% identical), C6 (8% identical), CR1 (7% identical), C7 (7% identical), F13B (6% identical), C8B (6% identical), CFHR5 (6% identical), and 27 more.
Diseases named in the same sentence as PAPPA in open-access papers:
PAPPA is named in the same sentence as 187 diseases in open-access papers, as found by Europe PMC text mining. Sharing a sentence is not in itself a finding about the gene and the disease. The quoted sentences say what the papers report.
preeclampsia (118 papers, 2008 to 2026). Preeclampsia is a hypertensive disorder of pregnancy that is characterized by new-onset hypertension with proteinuria presenting after 20 weeks of gestation, and depending on mild or severe forms may initially present with severe headache, visual disturbances, and hyperreflexia. "The glycoprotein PAPPA (Pregnancy-associated plasma protein A), produced by placental syncytiotrophoblasts, is linked to preeclampsia, with low maternal serum levels indicating a higher risk." (PMID 40974471, 2025). "Abnormally low PAPPA levels in first trimester maternal circulation are associated with increased risk of preeclampsia, a pattern also observed for another IGFBP protease, ADAM12." (PMID 21496272, 2011). "For example, circRNA_0001855 and circRNA_0004904 can not only involve in the pathology of preeclampsia by competitively binding miRNA but also predict preeclampsia even before 20 weeks of gestation (combined with PAPPA, total AUC = 0.940)." (PMID 33392159, 2020). "The most accurate predictor of PAPPA for preeclampsia was PAPP-A < 5th centile, with LR + 2.10 (1.57, 2.81), LR- 0.95 (0.93, 0.98); for SGA was PAPP-A < 1st centile; LR+ 3.50 (2.53, 4.82), LR- 0.98 (0.97, 0.99)." (PMID 26303460, 2015). "Several altered proteins, including PAPPA and ANG, were linked to preeclampsia." (PMID 40974471, 2025). "Additionally, SAA4, ANG, CFHR5, IGKV3-7, and PAPPA have been suggested to play a role in the context of preeclampsia." (PMID 40974471, 2025). "A study investigating the maternal proteome in preeclampsia via LC–MS/MS approaches reported on 17 differentially expressed proteins in the serum, from which our study also identified VWF, PAPPA, FCN3, and ITIH1 as candidates associated with the mode of conception." (PMID 40974471, 2025). "In addition to PAPPA2, we also measured levels of PAPPA and ADAM12 since they are also placental IGFBP proteases associated with preeclampsia and intrauterine growth restriction (IUGR), and IGFBP proteases may be coregulated." (PMID 21496272, 2011). "The mean serum PAPPA and PP13 levels in the first trimester were significantly lower in women with early preeclampsia (before week 34) compared to late preeclampsia (after week 34) (P < 0.005 and P < 0.04, resp)." (PMID 22778981, 2012). "A decrease in pregnancy-associated plasma protein A (PAPPA), a syncytiotrophoblast-derived metalloproteinase, and, in accordance with our results, an increase in PLAC1 expression was demonstrated in pregnancy complicated by preeclampsia as compared with non-PE controls." (PMID 36835024, 2023).
Down syndrome (50 papers, 2008 to 2025). "Circulating levels of PAPPA are elevated dramatically during pregnancy, and prenatal testing for low levels of PAPPA in maternal serum is currently used to screen for Down's syndrome and other aneuploidies." (PMID 20642865, 2010). "To date, PAPPA has been mainly used as a biomarker in prenatal screening for Down's syndrome." (PMID 26020769, 2015).
intrauterine growth restriction (37 papers, 2011 to 2026). "Another important function of MBP in the placenta is the inhibition of the pregnancy-associated plasma protein A (PAPPA), whose low levels are associated with intrauterine growth restriction." (PMID 31474955, 2019).
Hypertension (35 papers, 2016 to 2026). The presence of chronic increased pressure in the systemic arterial system. "Specifically, decreased PAPPA levels in the first trimester are associated with adverse pregnancy outcomes, while elevated serum PAPPA levels are observed in pregnant women with hypertension." (PMID 38082393, 2023). "Based on their disease–gene associations, these biomarkers are involved in vascular inflammation (HO-1, LPL, PAPPA, ADAMTS13, ADM, PGF, and GDF-2), hypertension, and arterial disease (PAPPA, ADAMTS13, ADM, and PGF)." (PMID 35327515, 2022).
atherosclerosis (34 papers, 2007 to 2025). A disease characterized by the build-up of fatty material and calcium deposition in the arterial wall resulting in partial or complete occlusion of the arterial lumen. "Pregnancy-associated plasma protein A (PAPPA), a zinc metalloproteinase, played significant roles in atherosclerosis." (PMID 33542956, 2021). "PAPPA was proposed as biomarkers and therapeutic targets for atherosclerosis according to our results." (PMID 33542956, 2021). "Moreover, circ-CHFR could contribute to human VSMC growth and migration as well as atherosclerosis deterioration via the circ-CHFR/miR-214-3p/PAPPA axis." (PMID 38515760, 2024). "Therefore, the role of PAPPA in atherosclerosis was worth investigating." (PMID 33542956, 2021). "For example, when PAPPA, the protease of IGFBP4, was genetically overexpressed in atherosclerosis models (APOE-KO), IGF bioavailability was enhanced due to reduced IGFBP4, resulting in a more severe atherosclerotic plaque formation." (PMID 36351970, 2022). "Moreover, five notable crosstalk pathways, circ-UBR4/miR-637/FOXO4, circ-UBR4/miR-107/ROCK1, circ-UBR4/miR-491-5p/NRP2, circ-UBR4/miR-185-5p/FRS2 and circ-CHFR/miR-214-3p/PAPPA axis, regulate VSMC migration and growth to improve atherosclerosis." (PMID 38515760, 2024). "Functional experiments provided insight into the function of the XIST/miR-98-5p/PAPPA axis in ox-LDL-mediated proliferation, apoptosis, and inflammatory response of HUVECs, which may imply a new molecular biomarker for atherosclerosis." (PMID 33542956, 2021). "Mechanistically, XIST could regulate PAPPA expression in ox-LDL-induced HUVECs by sponging miR-98-5p, providing understanding for atherosclerosis." (PMID 33542956, 2021).
diabetes (29 papers, 2014 to 2025). "Protein PAPPA was shown to be associated with risk of diabetes, to contribute to the development and progression of age-related degenerative changes, and to promote the longevity in case of its deficiency." (PMID 39847262, 2025). "Additionally, diabetes-associated genes such as TXNIP, SPON2 and PAPPA were upregulated." (PMID 33923831, 2021).
breast cancer (27 papers, 2009 to 2026). A primary or metastatic malignant neoplasm involving the breast. "Pregnancy-associated plasma protein-A (PAPPA) is highly expressed in pregnancy-associated breast cancer (PABC) tissues." (PMID 34974815, 2022). "Pregnancy-associated plasma protein-A (PAPPA) is a highly expressed protein in pregnancy-associated breast cancer (PABC) tissues." (PMID 34974815, 2022). "Comprehensive survival analysis of stromal ILC genes in human breast cancer datasets identified a positive association with improved survival and PAPPA and TIMP2 (tissue inhibitor of metalloproteinase 2) in ILC but not IDC." (PMID 35205651, 2022). "Gain- and loss-of-function experiments were performed in breast cancer cells to validate the functional role of PAPPA." (PMID 34974815, 2022). "Further analysis of breast cancer datasets showed that two of these genes which encode a secreted metalloproteinase (PAPPA) and a metalloproteinase inhibitor (TIMP2) were associated with survival outcomes in ILC." (PMID 35205651, 2022). "We next investigated the PAPPA gene locus, which is implicated in the development of mammary glands and is of interest in breast cancer studies and identified significant interactions in the 1 MB radius around the PAPPA gene using true and predicted counts." (PMID 31811132, 2019). "We next attempted to study the loss-of-function of PAPPA in breast cancer cells." (PMID 34974815, 2022). "Recent studies indicate PAPPA is frequently overexpressed in luminal B breast tumors and identify PAPPA as a pregnancy-dependent oncogene that promotes the formation of pregnancy-associated breast cancer." (PMID 31910858, 2020). "In this study, we investigated the potential role of PAPPA in modulating the malignant phenotype of breast cancer." (PMID 34974815, 2022). "Next, the functional role of PAPPA in breast cancer cells was validated by overexpression and knockdown experiments." (PMID 34974815, 2022). "Expression of PAPP-A in the TE has been reported in a number of different tumor types including breast cancer, and to verify that PAPPA was expressed predominantly by CAFs in ILC, we analyzed PAPPA transcripts by RNAScope." (PMID 35205651, 2022). "Through the loss-of-function and gain-of-function experiments, we demonstrated that PAPPA is indispensable for promoting the proliferation and metastasis of breast cancer cells in vitro and in vivo." (PMID 34974815, 2022). "In this study, we investigated the functional role of PAPPA in regulating the malignant phenotype of breast cancer." (PMID 34974815, 2022). "Previous studies have revealed that PAPPA expression is elevated in breast cancer cells, which promotes the proliferation, migration, and invasion of breast cancer cells." (PMID 34974815, 2022). "Overexpression of PAPPA promoted cell proliferation and metastasis of breast cancer cells in vitro and in vivo." (PMID 34974815, 2022). "Based on these results, our data suggest that miR-497-5p is a tumor-suppressor targeting PAPPA in breast cancer cell." (PMID 34974815, 2022). "To confirm the direct role of PAPPA protein on cellular function, we attempted to co-culture breast cancer cells with serum containing high level of PAPPA." (PMID 34974815, 2022). "Together, these data suggest that PAPPA functions as a tumor-promoting factor for breast cancer in vivo." (PMID 34974815, 2022). "As there are few cell lines that represent ILC, we first examined PAPPA across three integrated breast cancer cell line datasets." (PMID 35205651, 2022). "In this study, we aimed to investigate the potential role of PAPPA in regulating breast cancer progression." (PMID 34974815, 2022). "We further compared the expression levels of PAPPA in breast cancer cell lines (T47D, MCF-7, BT549, and MDA-MB-231 and MDA-MB-468) and normal breast epithelial MCF-10A cells." (PMID 34974815, 2022). "In contrast, breast cancer cells have been reported to become more invasive after down-regulation of PAPPA." (PMID 26020769, 2015).
breast cancer (continued). "A tumor growth-promoting role of PAPPA has been demonstrated in breast cancer ovarian cancer and lung cancer with mouse models very recently." (PMID 23896451, 2013). "Transgenic mice with mammary specific expression of the protease pappalysin-1 (PAPP-A), which is extensively overexpressed in breast cancers, have shown that extended lactation is protective against the oncogenic effect of PAPP-A, while abrupt halt of nursing increased its tumorigenic impact." (PMID 35163731, 2022). "Consistently, we showed that the injection of recombinant PAPPA protein could promote tumorigenesis and metastasis in the xenograft breast cancer mouse model." (PMID 34974815, 2022). "We also showed that silencing of PAPPA suppresses cell proliferation in breast cancer cells." (PMID 34974815, 2022). "Finally, we examined the impact of PAPPA on the tumorigenesis and metastasis of breast cancer in mice model." (PMID 34974815, 2022). "Finally, we validated the implication of PAPPA in the tumorigenesis and metastasis of breast cancer in mice model." (PMID 34974815, 2022). "In addition, PAPPA overexpression rescues the inhibitory impact of miR-497-5p on the cell invasion and migration in breast cancer." (PMID 34974815, 2022). "Therefore, PAPPA overexpression could abrogate the inhibitory effect of miR-497-5p on the cellular function of breast cancer cells." (PMID 34974815, 2022). "PAPPA could also regulate early mitosis and proliferation of breast cancer cells." (PMID 34974815, 2022). "To investigate the functional role of PAPPA in breast cancer cells, we transfected MDA-MB-231 and MCF7 with pcDNA-PAPPA plasmid to overexpress PAPPA." (PMID 34974815, 2022). "Further analysis of a panel of breast cancer cell lines showed that PAPPA was low or undetectable in all luminal cell lines, suggesting that a PAPP-A paracrine signaling axis is also present in other breast cancer subtypes." (PMID 35205651, 2022). "We first examined the expression level of PAPPA in PABC tissue and breast cancer cell lines using quantitative real-time polymerase-chain reaction (qRT-PCR) and western blot." (PMID 34974815, 2022). "We further identified miR-497-5p as a negative regulator of PAPPA, which suppressed cell proliferation, migration, invasion, and EMT in breast cancer cells." (PMID 34974815, 2022). "PAPPA was highly expressed in PABC tissues and breast cancer cells." (PMID 34974815, 2022). "Collectively, our study suggests that PAPPA is an oncogenic protein highly expressed in PABC tissues and promotes breast cancer progression, which could serve as a novel therapeutic target for breast cancer." (PMID 34974815, 2022). "We first examined the expression level of PAPPA in PABC tissue and breast cancer cell lines." (PMID 34974815, 2022). "Our study revealed that PAPPA was upregulated in PABC tissues and breast cancer cells." (PMID 34974815, 2022).
gestational diabetes (25 papers, 2013 to 2026). Carbohydrate intolerance first diagnosed during pregnancy. "Besides recurrent pregnancy loss the rs7020782 SNP in PAPPA also associates with the risk of gestational diabetes mellitus, risk of developing carotid plaques, and risk for ischemic cerebrovascular disease." (PMID 31519945, 2019). "More recent studies have shown that median PAPPA levels and β-hCG levels are decreased in women with pre-gestational diabetes." (PMID 26237386, 2014).
ovarian cancer (24 papers, 2012 to 2025). A primary or metastatic malignant neoplasm involving the ovary. "Through further analysis of these key genes and cancer stem cell subpopulation, more critical genes can be obtained as LCP2, FCGR3A, COL1A1, COL1A2, MT-CYB, CCT5, and PAPPA, are closely associated with ovarian cancer." (PMID 35360863, 2022). "Most ovarian cancer cell lines and primary tumors show partial or complete loss of expression of PAPPA." (PMID 23152806, 2012). "Differential display (DD)-PCR analysis comparing normal ovarian epithelial cultures and ovarian cancer cell lines identified pregnancy-associated plasma protein-A (PAPPA) as a CACG with frequent loss of expression in ovarian cancer cell lines." (PMID 23109895, 2012). "PAPPA is associated with the growth, invasion and metastasis of ovarian cancer." (PMID 35360863, 2022). "However, the functional role of PAPPA deficiency in ovarian cancer remains obscure." (PMID 23109895, 2012). "PAPPA, on the other hand, demonstrates dual roles, with its inhibition leading to decreased ovarian cancer cell growth, invasion, and metastasis, while overexpression can increase tumor growth." (PMID 37777759, 2023). "PAPPA is overexpressed in ovarian cancer, lung cancer, breast cancer, Ewing sarcoma, testicular and prostate cancer and hepatocellular carcinoma." (PMID 34350538, 2022). "Through the analysis of stemness-related key genes and tumor stem cell subpopulations, LCP2, FCGR3A, COL1A1, COL1A2, MT-CYB, CCT5, and PAPPA are closely related to ovarian cancer." (PMID 35360863, 2022). "Controversial roles of PAPPA have also been reported in ovarian cancer, with most ovarian cancer cell lines and primary tumors showing partial or complete loss of PAPPA expression." (PMID 26020769, 2015). "During the course of our study, PAPPA was over expressed in the SKOV3 ovarian cancer cell line by Boldt HB and Conover CA and they reported a tumor promotion effect of PAPPA." (PMID 23152806, 2012). "Additionally, we explored the detailed distribution of MGP, COL8A2, and PAPPA in ovarian cancer using single-cell RNA transcriptome data (GSE147082) from the TISCH database." (PMID 37777759, 2023). "Similarly, it has been found that overexpression of PAPPA in ovarian cancer cells promotes the growth of tumors." (PMID 34825509, 2021). "Therefore, COL1A1, COL1A2, MT-CYB, CCT5, and PAPPA may be potential genetic biomarkers for the treatment of ovarian cancer." (PMID 35360863, 2022). "How these proteins relate to the effect of LO remains to be uncovered, but a hint may lie in a previous report where genetic down-regulation of PAPPA by a protease inhibitor reduced ovarian cancer cell growth, invasion and metastatis via suppression of IGF-1-dependent Akt and ERK1/2 activation." (PMID 26161641, 2015). "In our new analytical process, the key genes related to ovarian cancer are identified as LCP2, FCGR3A, COL1A1, COL1A2, MT-CYB, CCT5, and PAPPA, which may have important significance in ovarian cancaer and drug therapy." (PMID 35360863, 2022). "The few available studies on other tumor entities located PAPPA expression to cancer rather than stromal cells, and controversial roles of PAPPA regarding tumor progression have been reported in ovarian cancer." (PMID 26020769, 2015).
acute coronary syndrome (23 papers, 2010 to 2026). Signs and symptoms related to acute ischemia of the myocardium secondary to coronary artery disease. "Pappalysin-1 is known as a metalloproteinase, mainly investigated as a marker of acute coronary syndromes or pathological birth disorders." (PMID 35269758, 2022).